TNF (tumor necrosis factor)
Diseases named in the same sentence as TNF in open-access papers (continued):
Sharing a sentence is not in itself a finding about the gene and the disease.
cancer (continued). "The analysis of mRNA expression in a co-culture of HFs and MG-63 cancer cells found a significant trend in the in vitro levels of TNF-α." (PMID 26418748, 2015). "Moreover, our results suggest that high serum resistin levels are related to cancer-associated chronic inflammation and support the previous study in which resistin exhibited pro-inflammatory properties by up-regulating the expression of TNF-α and IL-6 and the activation of monocytes." (PMID 26690142, 2015). "Although cachectic cytokines, such as TNF-α and IL-6, are elevated in the sera of cancer patients, clinical trials with one-target inhibitors have proven ineffective." (PMID 25972815, 2015). "On the other hand, adipokines including inflammatory cytokines such as interleukin-6 (IL-6) and tumour necrosis factor-α (TNF-α) as well as Zinc-α2-glycoprotein (ZAG) have also been associated with weight and fat loss in cancer." (PMID 26508820, 2015). "NF-κB/p65 is a downstream effector of the TNF signaling, which blocks TNF-mediated cell death and thereby provides cancer survival." (PMID 25779665, 2015). "Other studies also reported that antioxidants dose-dependently inhibit inflammatory markers like TNF- α and IL-1β in in vitro studies and their release from a human cancer cell line." (PMID 26262605, 2015). "For the extrinsic death receptors-triggered pathway, we successfully recovered one representative of cancer-therapy or drug-induced cell death pathway: TNF-induced apoptosis." (PMID 25883971, 2015). "TNFAIP2, which can be induced by treatment of TNF-α that with miR-184 can directly target TNFAIP2 in carcinoma (NPC) tissues, and is closely related to invasion and metastasis and poor survival in NPC patients." (PMID 25888093, 2015). "Specifically, TNFα stimulation or overexpression of RelA is sufficient to promote EMT of carcinoma cells." (PMID 26678048, 2015). "TNFα will activate the NFκB pathway which acts as a crossroad for the secretion of inflammatory factors in cancer." (PMID 25525301, 2014). "Expression level of Tumor Necrosis Factor—related apoptosis—inducing ligand (TRAIL) receptors is one of the most important factors of TRAIL-mediated apoptosis in cancer cells." (PMID 24979133, 2014). "Since MAP4K4 controls inflammatory signaling pathways downstream of TNFα and cancer cell motility, we investigated MAP4K4 functions in macrophages infected with T. annulata, which display a parasite-dependent chronic increase in TNFα expression." (PMID 24626571, 2014). "Although these findings suggest a role for TNF-α in lipolysis and proteolysis, its importance in cancer cachexia is an active area of debate." (PMID 24624094, 2014). "The link between chronicinflammation, such as gastritis or hepatitis and cancer, has long been establishedand TNFα has emerged as a suspect of promoting cancer progression under theseconditions." (PMID 28357238, 2014). "MTT assays were performed to investigate the effects of combining TNF-α with WA or Cel on MDA-MB-231 cancer cell proliferation." (PMID 25419573, 2014). "Therefore, it appears that one mechanism by which TNF and, in general, inflammation may cause cancer predisposition is a blockage of the differentiation fate in CSCs, at least partially preventing the generation of their fast-cycling destined-to-differentiate progeny." (PMID 25223735, 2014). "It has been also showed that the administration of anthracyclines to mice having cancer stimulates the secretion of tumor necrosis factor alpha (TNF-alpha) in neoplastic tissue." (PMID 24701565, 2014). "Second, the vicinity of cancer cells displays increased proinflammatory activity, through the detection of elevated levels of major cytokines such as the tumor necrosis factor (TNF)." (PMID 25601862, 2014). "Cancer cells can escape from cell death and survive by TNF-α in hypoxic and TGF-β-abundant condition, in contrast, TNF-α induced cell death in hepatocytes under HCV infection." (PMID 24505388, 2014).
cancer (continued). "TNF-a, the most extensively studied inflammatory factor in cancer, was proved to affect colorectal tumorigenesis through different pathways." (PMID 24404201, 2014). "Contrary to those studies, no change in mRNA expression of inflammatory markers including IL-6 and TNF-α were observed in SAT from cancer patients or in an animal model." (PMID 25415607, 2014). "The TNF superfamily of ligands and receptors, as well as TNF itself, are known to be modulated by HDACi’s in numerous cancer cell lines." (PMID 25054063, 2014). "Given the broad range of cancer-promoting activities of TNF-α, blockade of its signaling remains a tempting therapeutic approach." (PMID 24672527, 2014). "Regarding the mechanism of the hypercoagulability state in cancer patients, tumor necrosis factor, interleukin-1 and interleukin-6, which are released by monocytes or macrophages, lead to endothelial damage." (PMID 25103421, 2014). "In order to mimic the inflammatory conditions in cancer tissues, 10 ng/ml of TNF-α was used for each experiment in this study." (PMID 25419573, 2014). "In obese patients, TNF-α is suggested to be a key mediator of cancer-promoting inflammation in various organs, including the pancreas, colon, and liver." (PMID 24672527, 2014). "Recent evidence suggests that in cancer cachexia IL-1 and TNF-α mimic leptin signaling and interfere with the orexigenic response to reduced leptin levels." (PMID 24624094, 2014). "Owing to a high frequency of inflammation-related adverse events, the therapeutic applications of exogenous TNF-α in cancer have been quite limited." (PMID 24672527, 2014). "There is controversy, however, regarding the role of TNF-α in cancer; high concentrations of this cytokine can induce an antitumoral response in a murine model of sarcoma." (PMID 24901008, 2014). "The TNFα's impact on cancer also depends on the intracellular signal and thus is triggered in response to TNFα binding to its cell-surface receptor." (PMID 25525301, 2014). "Using these programs, we selected TNF-α as a miR-130a target gene for further study because of its ability to suppress cancer cell growth and to activate NF-κB." (PMID 24885472, 2014). "While AKT seems to be only slightly downregulated by DCE or CS, NF-κB is strongly inhibited by serquiterpene from Saussurea lappa, and NF-κB inhibition by DCE is known to enhance TNF-α-induced apoptosis of cancer cells." (PMID 25226283, 2014). "In summary, we show that BCG suppressed the apoptotic functions of TNF-α in many cancer cell lines thereby promoting tumorigenesis." (PMID 25208737, 2014). "As expected, some cytokines showed significant differences between healthy donors and pretreated cancer patients (IL-1β, IL-2, IL-6, TNF-α, and MCP-1)." (PMID 24800238, 2014). "CD40L inhibits in vitro melanoma cell proliferation by inducing their apoptosis or stimulating the production of cytokines that activate the immune system (IL-6, IL-8, TNF-α) by cancer cells." (PMID 25117071, 2014). "A recent retrospective cohort study evaluated overall mortality and cancer mortality in relation to immunosuppressive drug exposure, including anti-TNF drugs, in adult patients with ocular inflammatory diseases." (PMID 24405833, 2014). "Biological agents targeting inflammatory cytokines such as TNF-α have widely used in recent years as effective medications for treating AS, while numerous cases of the appearance of malignant tumors in patients receiving these drugs have been reported." (PMID 25070190, 2014). "The classically activated TAMs, the M1 phenotype, can be induced by interferon γ (IFNγ)/tumor necrosis factor α (TNFα) and exert a cytotoxic effect on cancer cells." (PMID 24507759, 2014). "According to these data, irradiated macrophages produce signals that include CD95 ligand, TNFα, nitric oxide, and superoxide, suggesting a model based on the intrinsic adaptability of immune and cancer cells in response to a genotoxic therapy." (PMID 24741617, 2014).
cancer (continued). "In line with suppression of the NF-κB pathway, we observed a concentration-dependent downregulation of the inflammatory and regulatory mediators TNF-α, IL10 and NO being implicated in development and progression of various cancers." (PMID 25271635, 2014). "The mechanism of action in cancer cachexia is not well understood but is likely related to the inhibition of IL-1, TNF-α, and leptin as well as the stimulation of NPY (Plata-Salamán, 1991)." (PMID 24624094, 2014). "Retinoblastoma protein (Rb), which can be induced by TNF-α, is an important oncogenic element leading to the aberrant expression patterns and proliferation of cancer cells." (PMID 25084809, 2014). "Inflammation is implicated in the progression of different haematological or non-haematological malignancies, and several pro-inflammatory factors, such as IL-6 and TNF-α, play a role in cancer development or progression." (PMID 24778454, 2014). "Results from studies measuring levels of TNF-α in patients with cancer cachexia have been conflicting." (PMID 24624094, 2014). "As already mentioned, some adipocytokines such as TNF-α induce increased angiogenesis, with angiogenesis being one of the key steps involved in the development of certain types of cancer, including CRC." (PMID 25019059, 2014). "Multiple pathways, including EGFR/PI3K/Akt, EGFR/mitogen-activated protein kinase, tumor necrosis factor-α and pro-metastatic matrix metalloproteinases are also involved in the mechanism by which EETs induce cancer cell proliferation and survival." (PMID 25406731, 2014). "Elevated serum concentrations of TNF-α have been described as a clinical feature of eight independent cancer types." (PMID 24672527, 2014). "To show the AGM-inducing factors in cancer vasculature, we investigated effects of TNF-α, TGF-β, VEGF, IL-6, and IL-8 on the expression of AGM protein by HUVECs in vitro." (PMID 24737780, 2014). "High expressions of PAI-1, MCP-1, TNF-α, uPA, VEGF and TIMP-1 have been associated with regional or distant metastasis and poor prognosis in cancer patients." (PMID 25356654, 2014). "Inflammatory cytokines, including tumor necrosis factor alpha (TNFα), interleukin-1beta (IL-1β) and IL-6, increase the invasive capacity of cancer cells." (PMID 24457902, 2014). "In our earlier works, co-immobilized TNF-α plus IFN-γ was prepared by this approach to synthesize a series of polymeric anti-cancer drugs." (PMID 24845203, 2014). "The aim of the study was to investigate the pre-operative serum levels of TNF-α and its correlation with cancer progression and survival in CRC patients taking into account the genotype of –308G/A promoter polymorphism in TNF-α gene (rs1800629)." (PMID 26019577, 2014). "from Philippine dairy products on cancer cells and normal fibroblasts and their effects on expression of early apoptotic-promoting cfos, cjun and proinflammatory cytokine IL-1β, TNF-α genes." (PMID 25276792, 2014). "Elsewhere, elevated serum cytokines and/or chemokines have been observed in cancer patients (such as TNF-α and IL-6), whilst others, like IL-12, are often down-regulated." (PMID 24520352, 2014). "Cancer cells that have been “primed” with TWEAK are sensitized to TNFα-induced cell death owing to the depletion of cIAP1 and TRAF2 proteins." (PMID 24550918, 2014). "Treatment of 18Co fibroblasts with the proinflammatory cytokine TNFα interfered with their ability to trigger STAT1 signaling in cancer cells." (PMID 24818101, 2014). "The total positive TNF-α expression rate in cancer tissue was 94% (105/112), and 84% (94/112) of cancer specimens were NF-κB positive." (PMID 24864130, 2014). "Gold nanoparticles conjugated with PEG and tumor necrosis factor alpha (TNFα are being developed for targeted cancer therapy." (PMID 25202689, 2014). "We further demonstrate that the combination of TNF-α with WA or Cel enhances their individual anti-cancer properties." (PMID 25419573, 2014).
cancer (continued). "TLR 7/8 agonists also support the induction of cancer-specific immunity by triggering an innate response characterized by the production of Th1 cytokines (including TNFα, IL-12, and IFNγ) and DC maturation." (PMID 24982761, 2014). "In particular, IR induces the secretion of the pro-inflammatory cytokines IL-1β and TNF-α in both animal cancer models and cancer patients." (PMID 25053129, 2014). "When compared with other cancer patient studies, the levels of TNF-α in our study were lower in both controls and cancer patients." (PMID 25163878, 2014). "Increased serum HP is a very frequent report in cancer, and is assumed as a marker of inflammation and tissue damage, mainly triggered by interleukins such as IL-6 and TNF-α." (PMID 24497876, 2014). "Application of TNF-α as potent cytokine for cancer biotherapy is due to its ability to mediate functions such as apoptosis." (PMID 25208737, 2014). "To evaluate the association between CIG expression and EMT we analysed 2 publicly available gene expression data sets of a time series of cancer cell lines treated with TGFβ alone (GSE17708) or in combination with TNFα (GSE12548)." (PMID 24586640, 2014). "The study did show an increased overall and cancer mortality in adult patients exposed to anti-TNF agents." (PMID 24405833, 2014). "We collected peritoneal washes or ascitic fluids on days 3, 7 and 10 after inoculation with cancer cells for the determination of TNF-α and IL-12 cytokines, which are secreted by M1 macrophages, and for the analysis of macrophage properties." (PMID 24992906, 2014). "In cancer cachexia, systemic inflammation is induced and persists due to increased tumor necrosis factor-alpha (TNF-α), interleukin-6 (IL-6), IL-1, and interferon-gamma (IFN-γ)." (PMID 25050383, 2014). "Our study indicates that BCG downregulates TNF-α-arbitrated apoptosis in the tested human cancer cell lines, A549, HCT116, T24, MNT-1, HepG2 and HELA." (PMID 25208737, 2014). "The results of our tests proved that the crude GpEPS preparation exhibited antitumor activity against carcinoma cells (lines SiHa) and stimulated production of Il-6 and TNF-α by macrophage line THP-1." (PMID 25114920, 2014). "The NF-κB pathway plays a central role in the regulation of immune responses and targets several inflammatory cytokines, such as TNF-α, IL-1, IL-6 and IL-8 and its aberrant activation has been identified in many cancer types." (PMID 23526956, 2013). "In humans, prospective epidemiological studies have also reported the association of high levels of interleukin-6(IL-6), tumor necrosis factor-alpha (TNF-α) and A-FABP, and low level of adiponectin, with cancer development." (PMID 24205276, 2013). "Inflammatory cytokines, particularly TNF-α, have been shown to be key mediators of cancer-related skeletal muscle degeneration." (PMID 24302570, 2013). "We further observed that the expression level of TNF-R1, the receptor of tumor necrosis factor-α, was unchanged in DAPs–treated cancer cells." (PMID 23663277, 2013). "To gain insights into the role of Rb in cancer-related skeletal muscle degeneration, we first examined the phosphorylation kinetics and subcellular localization of Rb in TNF-α-treated HSMMs." (PMID 24302570, 2013). "One possibility is that TNF-α interacts with a protein called Rb—short for retinoblastoma protein—that suppresses the proliferation of cells that leads to cancer." (PMID 24302570, 2013). "In the current study, we reported for the first time on how Ssd exhibits its anti-cancer effect through sensitizing TNF-α-induced cell death and suppressing TNF-α-induced NF-κB activation." (PMID 23573150, 2013). "The inhibitory effect of GMF on inflammatory factor NF-κB-mediated cancer progression was also revealed by decreasing the oncogenic potential of TNF-α-mediated cell migration, invasion, and EMT after GMF treatment of the SW620 cells." (PMID 24386633, 2013).
cancer (continued). "In hepatocytes, TNF modulates the nuclear location of C/EBPβ and its phosphorylation at Ser239, a process involved in oxidative stress and cancer-related cachexia." (PMID 23950892, 2013). "Prosurvival transcription factor nuclear factor-κB (NF-κB), for example, is a downstream effector of the TNF-α pathway, and is being regarded as a crucial factor during cancer initiation and progression." (PMID 27234396, 2013). "Alternatively, HSP70 has been reported to localize to the membranes of lysosomes, promote cancer cell viability, and inhibit TNF-induced cell death by inhibiting lysosomal membrane permeability." (PMID 24244355, 2013). "Vorinostat has synergistic effects against various cancer cells in combinations with decitabine, tumor necrosis factor, cisplatin, 5-fluorouracil, doxorubicin, and paclitaxel." (PMID 23864881, 2013). "For this purpose, we firstly investigated which cancer cell lines contain strong invasive activity in the presence of TNF-α." (PMID 23573150, 2013). "IL-6 and TNF-α are pleiotropic cytokines that function as autocrine or paracrine growth factors, which are secreted by normal prostate epithelial and cancer cells." (PMID 24168453, 2013). "Instead, inflammatory cytokines including IL-1 and TNFα are strong inducers of growth factor production by stromal cells, endothelial cells, and cancer cells as well as monocytes and T cells." (PMID 23936036, 2013). "Serum TNF-α and IL-6 increased otherwise in the group with severe cancer when compared to those of control, whereas IL-1β still kept steady among groups." (PMID 23349693, 2013). "The role of tumor necrosis factor alpha (TNF-α) in cancer is complex with both apoptotic and anti-apoptotic roles proposed." (PMID 23339680, 2013). "TNFα and IL-17 are commonly found together in the context of both acute and chronic inflammation; therefore, the effects of TNFα + IL-17 are biologically relevant to the inflammation-cancer interface." (PMID 23866118, 2013). "It is also reported that miR-21 and miR-31 are synergically induced by TGF-β and TNF-α, which facilitate cancer cell invasion." (PMID 23437179, 2013). "There is a growing area of research asserting that cancer- and cancer-treatment related fatigue is driven by pro-inflammatory cytokines (e.g., IL-6, IL-1β, TNF-α) and inflammatory pathways (e.g., CRP, IL-1RA) as observed using animal and clinical models." (PMID 23959120, 2013). "TNFα is frequently detected in many human cancer tissues including breast, ovarian, and renal cancers." (PMID 23997800, 2013). "On the other hand, for down-regulating TNF signaling, which is enhanced in several proinflammatory diseases and cancer, we performed the simulations for 12 in silico KOs of signaling molecules." (PMID 24199619, 2013). "IGFBP-3R, is involved in the inhibition of TNF-α induced NF-κB signaling cascade via the activation of caspases and eventual apoptosis in cancer cells." (PMID 23383064, 2013). "Collectively, these findings indicate that Ssd has a significant potential to be developed as a combined adjuvant remedy with TNF-α for cancer patients." (PMID 23573150, 2013). "TNF induced significant cell morphology changes; larger proportion of cancer cells become elongated and spindle shaped after TNF treatment." (PMID 23864892, 2013). "The contribution of NFκB signaling to the initiation and progression of cancer is clearly documented, and several lines of evidence demonstrate that TNF-α and/or NFκB signaling plays a key role in the regulation of EMT." (PMID 23437179, 2013). "αB-crystallin inhibits apoptosis in response to different anti-cancer agents, such as DNA-damaging drugs, TNFα and Fas ligand and has been shown to be a predictor of resistance to chemotherapy." (PMID 23506259, 2013). "TPL has been identified as a novel NF-κB inhibitor and has been shown to increase the efficacy of 5-fluorouracil (FU) and TNF in cancer cells through the inhibition of NF-κB activity." (PMID 24137468, 2013).